NES (nestin)
Diseases named in the same sentence as NES in open-access papers (continued):
Sharing a sentence is not in itself a finding about the gene and the disease.
tumor (continued). "Nestin and FLT1 expressions in RCC may be associated with aggressive tumor features and short patients’ overall survival." (PMID 39687450, 2024). "In addition, Nestin expression promotes tumor invasion via activation of epithelial-mesenchymal transition (EMT) pathways increasing cellular cytoskeleton flexibility and induction of integrin-dependent matrix degradation." (PMID 39687450, 2024). "Moreover, costaining of the tumor cells for SOX2 and nestin demonstrated that mHsp70 was also abundantly expressed (as well as CD133) on the tumor stem cells positive for these markers." (PMID 39015084, 2024). "Moreover, aCD19-SGRP CARs induced moderate antigen-independent killing of both EGFRvIII+ and NESTIN+ tumor cells, presumably due to a potential SGRP-mediated effect." (PMID 39521782, 2024). "Brain sections were stained with nestin antibody (a cellular marker for infiltration) for determination of invasiveness and nestin-positive cell clusters (>10 cells) distant from the primary tumor mass were counted." (PMID 39682088, 2024). "So nestin may mediate increased PNI in PDAC by raising tumor cells invading the nerve through the blood vessels and activating the VEGF signaling pathway." (PMID 38454277, 2024). "In addition, Sox2 expression was observed in primary tumor cells, while Nestin was expressed in recurrent tumors." (PMID 38256907, 2024). "Interestingly, we did not observe co-localization of ZO-1 with GLUT-1, but did observe co-localization of ZO-1 with Nestin, suggesting junction features between the stem/progenitor cells within the tumor." (PMID 39770529, 2024). "Multicolor murine imaging studies indicated that reporter-labeled stroma initially encircled clumps of tumor cells and then served as a scaffold that supported nestin-GFP-labeled endothelial haptotaxis resulting in encircling lymphangiogenesis, confirmed by dual LYVE1 immunofluorescence." (PMID 39669476, 2024). "Therefore, FGFR2-positive cHCC-CCAs and nestin-positive cHCC-CCAs share similar features such as smaller tumor size, the more frequent presence of CLC components, and multiple genetic alterations." (PMID 38532197, 2024). "However, no tumour or stem cell marker was consistently used across multiple studies to identify tumour to endothelial transdifferentiation, though Nestin was used slightly more frequently than other markers." (PMID 36823554, 2023). "Tumor cells with high Nestin and CD105 levels are acknowledged as CSCs." (PMID 37789353, 2023). "Since tumor expression of nestin could be easily evaluated by histologic analysis, such as IHC, incorporating nestin expression into the cancer histologic analysis may be of significance for the prediction of prognosis in patients with DTCs, such as GC and LC." (PMID 37485559, 2023). "NES is a gene that codes for nestin, an intermediate filament found in vascular endothelial cells that is upregulated in tumors to allow for increased angiogenesis at the tumor site." (PMID 37454191, 2023). "Tumour slides from 67 patients (radical prostatectomies) were stained for Nestin-Ki67." (PMID 37863961, 2023). "Second, nestin has been found to be involved in tumor angiogenesis, indicating that it may aid tumor growth." (PMID 37015965, 2023). "These tumor spheroids consisted of Nestin+ and Ki67+ cells, and the tumor stem cell niche." (PMID 37508868, 2023). "For all of the included studies, IHC was applied to detect the expression of nestin in cancer tissue, and various cutoffs were applied to define the higher expression of nestin, such as above medians, or nestin expression in >10%, 20%, or 50% of the tumor cells." (PMID 37485559, 2023). "Nestin may be a marker for newly synthesized tumor vessels and a therapeutic target for tumor angiogenesis." (PMID 36911388, 2023).
tumor (continued). "Quantification of cells revealed that SOX2+Nestin+ cells were significantly more abundant within the tumor bulk compared to the peritumor area (P = 0.01) whereas CD105+ Nestin+ cells were found dispersed without any significant difference in the density of distribution between the two regions." (PMID 36038950, 2022). "After establishing simultaneous immunofluorescence staining for CD133 and Nestin we investigated if a co-localization of both markers could be detected within the same tumor cells." (PMID 35183162, 2022). "Interestingly, we observed a significant overexpression of OCT4, SOX2, and NESTIN in both tumor KDM5C subgroups compared to the control samples." (PMID 36142158, 2022). "Nestin and Fascin double-positive tumor cells were detected." (PMID 35054386, 2022). "Since Nestin, CD44 and SOX2 are associated with stemness in GB, their elevated levels in the GB tumor samples suggested that these markers may drive the progression and radioresistance of GB." (PMID 35269397, 2022). "Thus, there are many studies on Nestin and Fascin, which clarify their histological origins, structures, and roles as useful biomarkers for various tumor malignancy." (PMID 35054386, 2022). "Nestin+ (neural stem cell marker) cells were frequently found in tumor spheroids but not as single cells, suggesting that the tumor spheroids are derived from tumor stem/progenitor cells among the initial dissociated cell mixture." (PMID 35381525, 2022). "Moreover, dedicated α-syn and nestin immuno-detection is needed in single patients to correlate the expression of α-syn with prognosis and malignancy of the tumor." (PMID 35326570, 2022). "Similarly, nestin expression was significantly greater at the tumor rim than the core in the MDA231Br-GFP tumors (matched Wilcoxon test, P < 0.001), although this was not replicated in the U87MG tumors." (PMID 35312755, 2022). "Furthermore, Nestin overexpression reversed the effect of miR-204-5p overexpression on suppressing the tumor growth." (PMID 35370458, 2022). "Furthermore, our data showed a trend for reduced survival in patients with high levels (> 40%) of Nestin expression in their initial tumor." (PMID 35183162, 2022). "In this study, we found that there exist numerous CD105+ cells outside of the tumor border but very few SOX2+ Nestin+ cells which may be considered as the main tumor cell component in patient peritumoral samples." (PMID 36038950, 2022). "Nestin prevents tumor cell death by inducing DNA damage repair." (PMID 35444938, 2022). "When the tumor sizes were compared, the differences among the six groups were not significantly different and IHC examination of stem cell (Nestin), neural (MAP2), glial (GFAP), cell proliferation (Ki67), and mitochondrial markers failed to reveal major differences as well." (PMID 34719887, 2021). "Nestin is a class VI intermediate filament protein, which is usually expressed by stem-like cells, including neural stem or progenitor cells, tumor stem cells and MSCs of various tissues." (PMID 34858970, 2021). "Tumors in the sh-NC groups had a higher mean tumor weight than those in the Nestin knockdown group." (PMID 34772403, 2021). "Additionally, expression of nestin in tumor cells is correlated with the malignancy of the tumor and with the cell capacity to form spherical aggregates, commonly called neurospheres or, more precisely, tumorospheres or oncospheres." (PMID 33916593, 2021). "It is intensely expressed in cancer cells with high metastatic capacity and, although it is demonstrated that nestin expression inhibition can reduce tumor cell metastatic capacity, the metastatic mechanism of this protein in cancer development is still not clear." (PMID 33805026, 2021). "To determine whether 2XSB cells maintained the immunophenotype of the parent tumor, we stained 2XSB cells for S100β, Sox10 and nestin." (PMID 33707600, 2021). "We determined the role of Nestin-mediated redox homeostasis and tumor phenotypes in GC cells." (PMID 34772403, 2021).
tumor (continued). "Tumor volume monitoring revealed that Nestin knockdown slowed the tumor growth rate." (PMID 34772403, 2021). "Nestin expression in tumor samples was determined by immunohistochemical staining." (PMID 34943921, 2021). "However, amongst our cases of AC, 25% of our cohort had an extensive expression of nestin in both the tumour islands and stromal cells." (PMID 33917771, 2021). "These annotations were used to predict the role of DCX, OLIG2, and NES in tumour biology." (PMID 34948016, 2021). "More significantly, collagen/fibronectin could facilitate the activation of PI3K/AKT/SOX2 and CDC42/YAP-1/NUPR1/Nestin signaling pathways via integrin αvβ3, eliciting sustained tumor growth and cancer relapse." (PMID 33408794, 2021). "In addition, we found that the expression of stemness genes was upregulated in the soft tumor cells (Nestin, OCT3/4 and SOX2 for 4T1/MCF‐7; Nanog, OCT3/4, SOX2, and CD133 for B16F1/MP‐1), while the BCL9L knockout reversed this effect (Fig EV5G)." (PMID 33274785, 2021). "Nestin has recently drawn attention as a marker for tumor angiogenesis." (PMID 32467665, 2020). "Also in vivo the expression of CD133 and Nestin is observed in ML/CT-2A tumors, indicating that the cells keep their stemness during tumor growth in mice." (PMID 33374542, 2020). "This cluster also enriched some well‐known stemness markers such as Sox11, Sox4, Nestin, Ptprs, and Cdk4, suggesting that they may function as the TICs in the tumor." (PMID 33173731, 2020). "(a) High CD133 and Nestin levels represent the abundance of cancer stem cells or stem cell‐like cells, which are capable of splicing symmetrically and asymmetrically into tumor precursor cells and contribute to heterogeneity of tumor." (PMID 31677196, 2020). "In addition, increased nestin expression was correlated with younger age, higher tumor grade, larger tumor size, positive blood vessel invasion and high vascular proliferation index, but not with lymph node metastasis or lymph vessel invasion." (PMID 32467665, 2020). "Among the 84 SCLC patients, 24 patients (28.6%) showed nestin-positive tumor." (PMID 32903755, 2020). "In these areas, SEL1L+ tumour cells corresponded to Nestin+ and Sox2+ cells." (PMID 31111685, 2020). "However, when cultured in sphere cultures the cells seem to increase their CD44 and Nestin expression, which was correlated with a more aggressive tumor behaviour in vivo." (PMID 33374542, 2020). "Moreover, CCL2 and CXCL10 was present in the tumor and the tumor microenvironment and co-localized with almost all Nestin+, Iba-1+, CD163+ or CD16+ cells, suggesting the same distribution and localization." (PMID 32943658, 2020). "Furthermore, YAP1-positive tumours in this early stage of development showed increased nestin expression and nestin was present in cells expressing nuclear YAP1 as well as those that had increased YAP1 in cytoplasm." (PMID 32404936, 2020). "In addition, we also detected the expression of NESTIN in tumor samples treated with CD19-BBz and NKG2D-BBz CAR- T cells and the results showed that NKG2D-BBz CAR-T cells significantly decreased the percentage of NESTIN-positive cells in tumors." (PMID 31288857, 2019). "Furthermore, by using RNA-ISH probes, we showed that APELA mRNA was expressed both in GBM tumor tissue and most interestingly in cells that co-express the stem cell marker Nestin." (PMID 30917521, 2019). "A possible reason for such varied expression of nestin may be due to the difference in tissue-specific progenitor cells and varying phenotype of tumor cells." (PMID 31675305, 2019). "In this study, we addressed the question whether different regulators of the dermal compartment such as CRABP1, Nestin, and Ephrin B2 are markers preserved directly in the surrounding tumour stroma of skin appendages tumours." (PMID 31065284, 2019). "We evaluated the presence of GSCs within the tumor by staining the brains for Nestin and CD133." (PMID 31511246, 2019).
tumor (continued). "Therefore, it is this total expression of Nestin within the tumor (and not only its tumorous component) that has a prognostic value in patients." (PMID 31511246, 2019). "In an attempt to kill both the differentiated and tumor initiating NB cells, this study demonstrated that a nestin targeted engineered clinically safe oncolytic virus (rQNestin34.5) promoted a profound cell death of both bulk and tumor initiating tumorsphere-derived NB cells." (PMID 31867574, 2019). "Indeed, inhibiting IL-8 with a function-blocking antibody not only reduced GBM tumor cell invasion by 55%, but also significantly diminished the number of nestin positive cells in GBM-endothelial cell co-cultures." (PMID 31227783, 2019). "In addition, our bioluminescent imaging demonstrated that Nestin knockdown rendered NSCLC cells more sensitive to 17-AAG in a subcutaneous tumor model in vivo, whereas the cytotoxicity of 17-AAG was attenuated in NSCLC tumors overexpressing Nestin." (PMID 31695040, 2019). "Furthermore, a recent finding showed that nestin-dependent regulation of Cdk5 occurs inside the nucleus, where nestin interacts with lamin A/C to maintain nuclear integrity and protect tumor cells from senescence." (PMID 31126068, 2019). "Interestingly, Nestin main expression was observed in the stroma interacting with tumour cells (TSI) and the invasive margin (IM), indicating an active role in reciprocal signalling between the tumour and the stroma cells." (PMID 31065284, 2019). "Consistently, immunoprecipitation assays and domain-mapping studies revealed that the C terminus of the Nestin rod domain (aa182–aa313) was critical for its interaction with lamin A/C, and downregulation of Nestin resulted in lamin A/C dispersion and degradation and then tumor cell senescence." (PMID 30190500, 2018). "At d138-d150, a highly infiltrating tumor with little mass effect on adjacent structures could be observed after staining for nestin." (PMID 30242200, 2018). "Importantly, we also found that AMG232 is highly efficacious in three-dimensional (3D) tumor spheroids growth and effectively inhibits the stemness-related factors, Nestin and ZEB1." (PMID 30022047, 2018). "Moreover, expression of Nestin was reported to be upregulated in most mitotic cells, including tumor cells and cancer stem cells, and downregulated upon differentiation." (PMID 30185144, 2018). "The nuclear import of Nestin suggested that it could directly regulate lamin A/C-dependent nuclear deformation and tumor senescence." (PMID 30190500, 2018). "Notably, only a specific type of pericyte, expressing both NG2/CSPG4 and Nestin, would be recruited during tumor angiogenesis." (PMID 30213051, 2018). "Previous reports suggest nestin is a specific marker for angiogenic EC in various tumour types, and could be useful as a therapeutic target." (PMID 30279450, 2018). "BRCA1 positive cases more often had Nestin positive tumours, compared with cases without BRCA1 germline mutations, OR (odds ratio) 8.7 (p < 0.0005, Series III), with a sensitivity of 62% and specificity of 84%." (PMID 28439082, 2017). "Cytoplasmic nestin expression in tumor cells was observed in 28 of 90 (31.1%) NSCLCs." (PMID 28358810, 2017). "Similarly, nestin staining revealed that 6OTD treatment led to 60% (10 pmol) and 81% (100 pmol) reductions in tumor size (bottom)." (PMID 28620243, 2017). "Interestingly, confocal microscopy analysis of human GBM specimens showed that PATZ1 was expressed in the NESTIN+ subpopulation, which has been recently shown to be crucial for tumor recurrence after treatment with the chemotherapeutic agent temozolomide." (PMID 28938636, 2017). "Similarly, the number of diffusely infiltrating tumor cells that stained positive for nestin significantly decreased in CLOVA cocktail-treated mice." (PMID 28423558, 2017).
tumor (continued). "During responsiveness to Bev, probably because oxygen demand by the tumor decreases, hypoxic markers (HIF-1α and CA9) and the marker for stem cell and vascular proliferation (nestin) are decreased, suggesting that tumor oxygenation is preserved; thus, VEGF and its receptors are relatively reduced." (PMID 29262608, 2017). "Given that nestin-positive tumor cells have characteristics of CSCs, those nestin-positive tumor cells may be resistant to chemotherapy." (PMID 28358810, 2017). "In our study, TJ905 tumor stem cells were isolated with the magnetic activated cell sorting method and the characteristics of the cancer stem cells were identified using immunofluorescence staining for nestin, β-tubulin, and GFAP." (PMID 28955297, 2017). "Together, our findings show that expression of mutant Idh1 recapitulates cellular and molecular features of gliomagenesis, including stem cell features, increased proliferation, infiltration into adjacent structures, and tumor-like nodules originating from nestin-expressing cells." (PMID 27693047, 2016). "However, numerous nestin-positive tumor cells remained after Bev treatment, with relative concentration around vessels." (PMID 27244880, 2016). "The expression of VEGFR2 (a marker of capillary endothelial cells) and nestin (a marker of pericytes) was significantly decreased in all of the post-sunitinib samples, thus corroborating the activity of sunitinib on the tumour micro-environment." (PMID 27304187, 2016). "Interestingly, nestin was the only stem cell marker expressed by the invasive tumor cells of all three GSS cultures suggesting a function of nestin in these cells, which is in line with previous findings of nestin being important in invasion." (PMID 27454178, 2016). "However, there were still numerous nestin-positive tumor cells in the six tumors, and these positive cells were relatively concentrated around vessels." (PMID 27244880, 2016). "In addition, elevating of miR-92a also resulted in a marked reduction in the expression of cancer stem-like cells marker CD133 and Nestin, which is consistent with the inhibitory effect of miR-92a-3p on the tumor spheres formation capability of GSCs." (PMID 27801803, 2016). "Nestin, indeed, is a marker of multipotent neuroectodermal precursor cells, expressed in a cell-cycle-dependent manner, and its overexpression is related to tumor aggressiveness, including NB." (PMID 27014421, 2016). "Additionally, tumor cells express Nestin, a neural stem cell (NSC) marker that is activated during malignant transformation of OPC22." (PMID 25683249, 2015). "Weak nestin expression was correlated with favorable tumor features." (PMID 25371063, 2015). "Production of CCL2, which could induce a large amount of accumulation of MDSCs through CCR2, is strongly increased in tumor-bearing mice, and nestin+ splenocytes clearly participate in the increase in chemokine production in tumor- bearing hosts." (PMID 26161081, 2015). "Nestin was expressed in <50% of the tumor cells with GFAP expressed throughout." (PMID 25919028, 2015). "CD133 and nestin were reported to be markers of most tumor SLCs." (PMID 25760394, 2015). "In the present study, U87 spheres were found to be positive for CD133 and nestin; in addition, the cultured tumor spheres were able to differentiate into cells positive for GFAP, β-tubulin III and Galc, therefore suggesting the successful induction of U87 SLCs." (PMID 25760394, 2015). "In MPM, any nestin expression was observed in 13% of the tumor cells of 6 epithelioid MPM." (PMID 26421614, 2015). "However, using tumor staining for Olig-2, Nestin and GFAP, we demonstrated that our preclinical model represents a range of GBM cell types, therefore modeling the heterogeneous cell population in human GBM." (PMID 25431423, 2015). "Weak nestin expression was correlated with favorable tumor characteristics and a good prognosis." (PMID 25371063, 2015).